STAT1 (signal transducer and activator of transcription 1)
Diseases named in the same sentence as STAT1 in open-access papers (continued):
Sharing a sentence is not in itself a finding about the gene and the disease.
viral infection (continued). "Upon viral infection, IKKε can be activated by the unanchored K48-linked polyubiquitin chain generated by TRIM6, leading to downstream STAT1 activation." (PMID 39823515, 2025). "Intriguingly, under conditions of viral infection or direct interferon stimulation, DHX9 uniquely associates with the ISG promoter region, facilitating STAT1-mediated transcription of a of ISGs67." (PMID 38594251, 2024). "Despite the established role of autophagy in CSFV replication, the specific function of STAT1 in the regulation of autophagy during this viral infection remains largely unexplored." (PMID 39539545, 2024). "STAT1 and its activation through phosphorylation are essential for the host immune defense, especially in the context of viral infections." (PMID 38702815, 2024). "This study showed that the absence or reduction of STAT1 significantly enhanced autophagy during viral infection." (PMID 39539545, 2024). "Research conducted on a neuroblastoma cell line revealed that STAT1-dependent inhibition of viral infection and replication occurred." (PMID 38994355, 2024). "Among the hub-sDEGs, the signal transducer and activator of transcription 1 (STAT1) is essential for the defense against viral infections like influenza A and SARS-CoV-2 infections." (PMID 39024368, 2024). "Both of these factors are known to form a complex, which as a chaperone can enhance the type I IFN response mediated by STAT1 in response to viral infection." (PMID 39110744, 2024). "Existing literature has provided evidence that increased levels of HO‐1 inactivate STAT1 in response to LPS stimulation or viral infection." (PMID 38617435, 2024). "Viral infections interact mainly with the activated Signal Transducer and Activators of Transcription 1, 2, and 3 (STAT1, STAT2 and STAT3) to release pro-inflammatory cytokines to eliminate viruses." (PMID 38628843, 2024). "First, signal transducer and activator of transcription 1 (STAT1) inborn errors were reported in two infants who succumbed to a lethal viral disease together with mycobacterial dissemination, but the viral etiology of the second infant remained unclear." (PMID 38997413, 2024). "STAT1, as a key factor in controlling viral infection, can be degraded by CRLs, in which Paramyxoviruses V protein and respiratory syncytial virus nonstructural proteins serve as substrate receptors." (PMID 38005838, 2023). "STAT1 is a transcription factor involved in immune system activation in response to viral infection, and it has been shown to promote tumor growth and survival." (PMID 37834191, 2023). "Our data revealed that PAC5, a highly selective and potent agonist of hnRNPA2B1, initiates the TBK1-IRF3 pathway leading to upregulation of type I IFNs, phosphorylation of STAT1/2, and inhibition of viral infection in vivo and in vitro." (PMID 36726760, 2023). "Here the authors identify a population of fibroblast cells that can support murine cytomegalovirus lytic and latent virus infection in vivo and propose STAT1 as critically involved in murine cytomegalovirus latency." (PMID 37248241, 2023). "The adaptive behavior of NK cells during viral infection is facilitated through STAT1-mediated epigenetic control of RSAD2." (PMID 38162574, 2023). "Another E3 ubiquitin ligase TRIM18 recruited protein phosphatase 1A (PPM1A), a negative regulator of STAT1, to dampen type I interferon-mediated antiviral innate immunity for promoting virus infection." (PMID 36817462, 2023). "For all therapies, the risk of adverse events must be considered, such as increased incidence of viral infections in STAT1 GOF during JAK inhibitor use or fatal outcomes in HSCT of STAT3 GOF patients." (PMID 37140667, 2023). "Later during viral infections STAT1 protein level increases and takes the lead role in IFN signaling." (PMID 36826612, 2023). "Since natural killer (NK) cells are pivotal for viral clearance, a STAT1 GOF can alter NK cell function during viral infection." (PMID 36826612, 2023).
viral infection (continued). "Ultimately, this is thought to mimic a STAT1 LOF phenotype known to be associated with recurrent mycobacterial and viral infections." (PMID 37140667, 2023). "Among the three STAT members identified, STAT1 showed highest fold change and it was consistent with previous finding that STAT1 contributes to innate immune response during viral infection." (PMID 37709257, 2023). "For example, interferon-induced JAK-STAT signaling is activated in response to Hepatitis C virus, Chikungunya virus or Sindbis virus, and viral proteins modulate STAT1 protein expression for viral infection in mammalian cells." (PMID 36928081, 2023). "A STAT1 LOF mutation must be considered when evaluating patients with the clinical picture of severe mycobacterial and viral infections." (PMID 37140667, 2023). "In conclusion, our study reveals that STAT1 is a sumoylation substrate of RanBP2, and that RanBP2 facilitates viral infection by attenuating interferon-α-induced antiviral innate immunity, likely by sumoylating STAT1." (PMID 38203469, 2023). "The stark response to viral infection shown in the transcriptional increase of factors such as Ifitm2, Irf7, Stat1, and Eif2a, among others, indicates a heart actively mounting a host response to the invading SARS-CoV-2." (PMID 37081485, 2023). "Of interest, overexpression of full-length lncRNA-155 resulted in the highest activation of STAT1 after virus infection." (PMID 36321836, 2022). "Significant STAT1 phosphorylation and STAT1/STAT1 homodimerization during viral infection has also been reported." (PMID 35634328, 2022). "Partial or complete autosomal recessive (AR) STAT1 deficiency disrupts the IFN-α/β and IFN-γ signaling pathways, which predisposes such patients to weakly virulent intracellular bacterial and viral infections (Immunodeficiency 31B, OMIM #613796)." (PMID 36339330, 2022). "Now, there are studies which pointed out that IL-27 can inhibit viral infection by activating STAT1/3 and CXCL9/10." (PMID 35785034, 2022). "Both miRNA-155 and lncRNA-155 can upregulate the phosphorylation of STAT1 during the viral infection." (PMID 36321836, 2022). "Together, these data demonstrate that STAT1-deficient HSCs at steady state have reduced expression of MHC molecules, IFN-stimulated genes, genes involved as defense against viral infection, and those involved in viral sensing/tumor immunosurveillance." (PMID 35767701, 2022). "LOF mutations in STAT1 and TYK2 increase susceptibility to bacterial and viral infections, while LOF in STAT2 increases the incidence of viral infections and LOF in STAT4 increases the incidence of fungal infections." (PMID 35337171, 2022). "Several studies have shown the central role that STAT1 plays in the immune response against viral infections by transducing in the nucleus the signal from type I, type II and type III IFNs." (PMID 35456913, 2022). "SIGLEC1 has been reported to be up-regulated upon viral infection through the IFN/JAK/STAT1 signaling pathway, which spreads the infection and helps virus to escape from neutralization." (PMID 35470857, 2022). "As predicted, miRNA-155-5p overexpression resulted in increased activation of STAT1 (p-STAT1 Y701) following viral infection compared to the control." (PMID 36321836, 2022). "Taken together, these results confirmed that hPL inhibits viral infection by activation of the cellular antiviral STAT1 pathway." (PMID 35891479, 2022). "The expression of this protein increases with viral infection and is related to increased STAT-1 signaling and decreased IFN responses." (PMID 36429055, 2022). "While it is known that STAT1 is required for ISG induction upon virus infection of mice, we, to our knowledge, are the first to describe the enrichment of the STAT1 DNA binding motif among promoter regions of late-responding genes upon CpG activation of pDCs." (PMID 34544361, 2021).
viral infection (continued). "STAT1 is a key transcription factor activated by type I IFN signaling and Stat1-/- mice are useful in establishing virus infection models, including those for the study of the DENV and Zika viruses." (PMID 33784371, 2021). "In the lung, Stat1−/− mice develop enhanced Th2 inflammation in mouse models of fungal and viral infections." (PMID 34755542, 2021). "HSCT was performed for 25 patients with STAT1 GOF mutation to treat severe persistent CMC and bacterial infection, systemic viral infections, and severe inflammatory conditions." (PMID 33777053, 2021). "Next, we tested the effect of LPS on the phosphorylation profile of NFκB, ERK1/2, JNK, TBK1 and Stat1 when applied 24 h after virus infection." (PMID 34975859, 2021). "It has been shown that STAT1−/− C57BL/6 mice fail to mount efficient responses to IFN and they are susceptible to viral infections." (PMID 33920517, 2021). "Fully functional STAT1 is crucial to protect the nervous system from neurotropic virus infection and immunopathology." (PMID 34653236, 2021). "Virus infection can induce the upregulation of HOIP to enhance HOIP-mediated Met1-linked ubiquitination of signal transducer and activator of transcription 1 (STAT1)." (PMID 33288901, 2021). "More specifically, BRCC36 deficiency leads to a rapid downregulation of STAT1 during viral infection, whereas complementation by BRCC36 can rescue the STAT1 expression levels and suppress virus infection." (PMID 34707613, 2021). "The results showed that STAT1 linear ubiquitination was gradually downregulated after 1 h of viral infection, which is consistent with IFNβ induction by viral infection." (PMID 32123171, 2020). "In humans, viral infection activates the type-I interferon (IFN-I) signaling leading to STAT1/2 activation." (PMID 31936331, 2020). "It has been reported that the STAT1-deficient mice were more susceptible to severe acute respiratory syndrome (SARS) and other viral diseases and displayed more serious lesions." (PMID 33344524, 2020). "High levels of type I, II, and III interferons are produced during viral infection and all signal through STAT1." (PMID 32397226, 2020). "Activation of p38 and JNK was reported to regulate the inflammatory response to viral infections mediated by NF-κB, c-Jun, and STAT1." (PMID 33081802, 2020). "IFNs activated STAT1 is a target for ubiquitylation and degradation during multiple viruses infection." (PMID 32532301, 2020). "IL-27 strongly induced STAT1-dependent pathways and weakly induced STAT3-dependent pathways implicated in flaring up the viral infection and HCC progression in liver viral infection, suggesting the probable use of IL-27 as a safe treatment in viral hepatitis." (PMID 33381596, 2020). "Given that viruses rapidly induce IFN production, we further observed the dynamic regulation of STAT1 linear ubiquitination during the early stage of viral infection." (PMID 32123171, 2020). "The MERS-CoV-shared genes KRT6B and TNFAIP3 had a high p-value associated with SARS-CoV-2, whereas genes such as OAS1-3, IRF9, IRF7, STAT1, PML and IFIH1 were highly associated with host responses to viral infections and type I interferon." (PMID 33301474, 2020). "These viral infections seem to recruit STAT1/2 proteins to the CUL4A-based ubiquitination complex for the proteasomal degradation of STAT1/28." (PMID 32973222, 2020). "Most of these DEGs were associated with the host response to virus infection and type I interferons, while others such as IRF9, PML, IRF7, STAT1 and IFIH1 were related to interferon signaling." (PMID 33301474, 2020). "Overall, our findings demonstrate the key contribution of STAT1 in modulating innate and adaptive immunity during type I interferon-mediated lethal virus infection." (PMID 32310998, 2020). "Viral infection can inhibit IFN-STAT1 antiviral signaling by stimulating HOIP expression via the NF-κB pathway and resulting in STAT1 linear ubiquitination." (PMID 32123171, 2020).
viral infection (continued). "This is consistent with previous finding that u-STAT1 can shuttle between cytoplasm and nuclear and reinforces host defense against viral infection." (PMID 30456450, 2019). "Specifically, we demonstrated that STAT1 and other key regulators are activated upon viral infection and/or poly I:C treatment, and that engineering the regulation of innate immunity aids in viral resistance." (PMID 31222165, 2019). "We did not explore the mechanisms behind the increased STAT2 level in GOF patients, but this is an important future research direction, especially given the difficulties with viral infections in STAT1 GOF disease." (PMID 31354696, 2019). "In this study, we demonstrated that NDR1, a positive regulator of ISGs induction, is downregulated after viral infection via STAT1 signaling." (PMID 30018336, 2018). "Upon viral infection, type I and type II interferons (IFNs) initiate a canonical antiviral transcriptional program through STAT1 and STAT2, which results in an inflammatory, proapoptotic, and antiproliferative state." (PMID 29543893, 2018). "Other members of the network also reappeared in the gene set enrichment analysis as members of pathways associated with viral infections (DDX58, IFIT1, IRF1, MX1, STAT1) or viral carcinogenesis and cell cycle (CCND1, CCND3, CCNE1, CDC20, E2F2, RANBP1)." (PMID 30042828, 2018). "Here, we identified metabolite-sensing GPCR TGR5 as an interferon (IFN)-stimulated gene (ISG) which had increased expression following viral infection or IFN-β stimulation in a STAT1-dependent manner." (PMID 30333836, 2018). "We also found that STAT1/2 was highly activated in HFDPCs with low MOI of DENV-2 infection (MOI = 1), but this high level of STAT1/2 phosphorylation was decreased in cells with high MOI of virus infection (MOI = 5 and 10)." (PMID 30186771, 2018). "Viral infection upregulates TGR5 expression in an IFN/STAT1-dependent manner which in turn amplifies the antiviral innate immune responses via AKT-mediated IRF3 activation." (PMID 30333836, 2018). "So far, serine monophosphorylation induced by virus infection has been only reported for STAT1 and STAT3." (PMID 29662014, 2018). "Taken together, these data suggest that viral infection upregulates TGR5 expression in an IFN/STAT1-dependent manner, which can be recognized as an interferon (IFN)-stimulated gene (ISG)." (PMID 30333836, 2018). "For example, signal transducer and activator of transcription 1 (STAT1) or nuclear factor (NF)-κB essential modulator (NEMO) deficiency leads to lethal HSV disease and various other severe viral infections." (PMID 30319615, 2018). "Viral infection induced a number of genes and proteins in the signaling pathway upon viral infections, we found that Mx1 and STAT1 mRNA levels can be induced in acute HIV-1 infection." (PMID 28623917, 2017). "To date, serine mono-phosphorylation induced by virus infection has only been reported in STAT1 and STAT3." (PMID 29312301, 2017). "The available data imply a correlation between serine mono-phosphorylation of STATs (STAT1 and STAT3) and the proinflammatory response caused by virus infection." (PMID 29312301, 2017). "Chronic mucocutaneous candidiasis is the most frequent infection associated to STAT1 GOF mutations, although patients have also bacterial and viral infections." (PMID 29270166, 2017). "STAT1-Dependent Genomic Response of Neurons has been studied extensively in the context of viral infections that lead to neurodegeneration." (PMID 28774347, 2017). "In this study, the expression of Mx1 gene, important for resistance against viral infection, and STAT1 were significantly induced." (PMID 28349053, 2017). "Recent studies have shown that type-I IFN and STAT1 are required for NK cell responses following viral infection." (PMID 29181006, 2017). "During virus infection C6 reduces ISRE-dependent gene expression despite the presence of the viral protein phosphatase VH1 that dephosphorylates STAT1 and STAT2." (PMID 27907166, 2016).
viral infection (continued). "We demonstrated that IL-27, a key cytokine in generating immunity against bacterial and viral infection, also depends on STAT1 to suppress TH2 cell differentiation." (PMID 27687913, 2016). "Using confocal microscopy, we measured nuclear translocation of phosphorylated STAT1 (pSTAT1) in uninfected BHK-21 cells surrounding foci of viral infection." (PMID 27185466, 2016). "Using the ISGylation-deficient Ube1l−/− cells, we found that UBE1L suppresses basal STAT1 activity in the overall population of the cells, but also increases the resistance against the viral infection." (PMID 27427993, 2016). "The expression of ISG15, the enzymes responsible for its conjugation, and cellular target proteins such as DDX58, IRF3, PKR, and STAT1 are strongly induced by treatment of type I IFNs or viral infection." (PMID 27427993, 2016). "The results of these studies indicate that in addition to its pivotal roles in preventing viral infections and inhibiting cell growth, STAT1 modulates lipid metabolism, energy expenditure and mitochondrial biogenesis." (PMID 26689548, 2015). "The ratio of STAT1:STAT4 is also an important determinant of the CD8+ T cell response upon virus infection." (PMID 24489749, 2014). "STAT1 is the best characterized transcription factor known to regulate many of the biological effects mediated by IFNs in response to viral infections in vivo." (PMID 24788809, 2014). "Signal transducer and activator of transcription (STAT) proteins are transcription factors that are important in IFN signaling; genetic defects in STAT-1 result in death by viral disease at an early age." (PMID 23633945, 2013). "Both NF-κB and STAT1 are rapidly activated in response to various stimuli including viral infection and cytokines, thus controlling the expressions of anti-apoptotic, pro-proliferative and immune response genes." (PMID 23191987, 2012). "During viral infection, production of interferons and cytokines leads to phosphorylation and homodimerization of STAT1 or heterodimerization of STAT1 with its β isoform." (PMID 22383882, 2012). "STAT1, which plays a significant role in activation of innate immune response to viral infection, was further studied for protein expression using Western blotting." (PMID 21439068, 2011). "To further validate the differences in the host immune responses to seasonal H1N1 and pH1N1 virus infection, we studied the expression of STAT1 protein." (PMID 21439068, 2011). "STAT1 protein is an important component of Jak-Stat pathway which gets activated at later stages of virus infection." (PMID 21439068, 2011). "We propose a new potential pathway by which STAT1 regulates end stage lung disease following viral infection." (PMID 20386712, 2010). "Differential expression of STAT1 in the two virus infections observed in our study also indicate higher cytokine mediated inflammatory responses in WB-NIV2664 infection than the modified strain." (PMID 20828378, 2010). "Following rMA15 virus infection, STAT1−/− mice lost 15% of their starting weight by day 4 and continued to lose weight through day 9 post-infection." (PMID 20386712, 2010). "Specifically, we aim to investigate whether RIOK3 participates in the JAK1/STAT1 pathway, which is central to the interferon response to viral infections." (PMID 40371100, 2025). "Moreover, STAT1 mRNA and protein levels were up-regulated in the transfection group and virus infection group." (PMID 40001503, 2025). "Heterozygous LOF mutations in STAT1 are rare and lead to increased susceptibility to mycobacterial infections without predisposing to viral infections, this can be explained by an impaired response to IFN-γ, while IFN-α/β signaling remains preserved." (PMID 41438753, 2025). "Moreover, the STAT1 mRNA and protein levels were significantly increased in both the transfection group and virus infection group." (PMID 40001503, 2025).